DDX11L10 (DEAD/H-box helicase 11 like 10 (pseudogene))
Synonyms: formerly DDX11P; DDX11L1
Gene: Transcribed unprocessed pseudogene on chromosome 16 (11,861 to 13,351, forward strand). Ensembl gene ENSG00000233614.
Diseases named in the same sentence as DDX11L10 in open-access papers:
DDX11L10 is named in the same sentence as 1 disease in open-access papers, as found by Europe PMC text mining. Sharing a sentence is not in itself a finding about the gene and the disease. The quoted sentences say what the papers report.
Cryptococcal meningitis (1 paper, 2019). Meningeal inflammation produced by cryptococcus neoformans, an encapsulated yeast that tends to infect individuals with acquired immunodeficiency syndrome and other immunocompromised states. "The expression of the lncRNAs, ECRP, LINC00968, DPY19L1p1, DEFA8P, and DEFT1P2 was higher but the expression of the lncRNAs DDX11L10 and MTMR9LP was lower in cryptococcal meningitis patients than in healthy controls, which was consistent with the chip analysis results." (PMID 30767376, 2019).